PRL (prolactin)
Diseases named in the same sentence as PRL in open-access papers (continued):
Sharing a sentence is not in itself a finding about the gene and the disease.
adenoma (continued). "The addition of cabergoline to somatostatin analogue therapy may improve response in patients who otherwise are not fully controlled by maximal doses of somatostatin analogues, and in patients with adenomas co-secreting GH and prolactin." (PMID 20478050, 2010). "Dopamine agonists can be considered in patients with a prolactin co-secreting adenoma." (PMID 20478050, 2010). "Some adenomas are mixed; mixed GH- and prolactin (PRL)-secreting adenomas occur frequently (25%)." (PMID 19660127, 2009). "Mixed GH- and prolactin (PRL)-secreting adenomas are frequent (25%)." (PMID 18578866, 2008). "Some adenomas contain both cell types, while other develop from a mammosomatotropic stem cell and consist of more mature monomorphic cells that express both GH and PRL." (PMID 18578866, 2008). "Moreover, SSTR1-expressing cells from GH- and PRL-secreting adenomas and medullary thyroid cancer exhibited inhibition of hormone secretion in addition to reduced cell viability in response to SSTR1-specific agonist." (PMID 16018813, 2005). "However, we did identify a significant positive association between adenoma size and volume and the time required for prolactin normalization, although this was not the case for baseline prolactin levels." (PMID 38645431, 2024). "The primary treatment strategy (i.e., TSS or DAs), patient age, cardiovascular risk factors, baseline PRL levels, and the prevalence of macroprolactinoma or adenomas with cavernous sinus invasion were not significantly different between patients with and without ED." (PMID 39085672, 2024). "Thus, PRL-secreting adenomas were excluded from the subsequent analysis of the GTR rate." (PMID 37025271, 2023). "Additionally, this might be associated with previous medical treatment with dopamine agonists for PRL-secreting adenomas, which facilitate fibrous tissue formation." (PMID 35807204, 2022). "We hypothesise that this effect could be due to its specific cluster of aromatic residues, opening the possibility of using this analogue to inhibit prolactin secretion in prolactin-secreting adenomas since these roles are ascribed to specific functions of the SST receptor 540,41." (PMID 33767180, 2021). "In addition, compared with GH-producing adenomas, PRL-, ACTH-, and TSH-producing adenomas could yield inferior contrast between the adenoma and normal pituitary gland when searching for microadenomas on dynamic MRI." (PMID 33881731, 2021). "Follow-up at < 24 months in a few patients may have interfered with the results of long-term dependence on DAs, as our treatment regime consisted of tapering medications 24 months after initiation of the medical therapy if PRL levels had normalized and/or adenoma reduction of > 50% was attained." (PMID 33847973, 2021). "However, none of the factors (prolactin before withdrawal, menopausal status, treatment duration, complete adenoma regression) showed a correlation with recurrence risk in multivariate analysis." (PMID 31001736, 2019). "However, according to WHO's recommendations, the gonadotropinomas releasing luteinizing hormone (LH) and follicle-stimulating hormone (FSH), along with the prolactin secreting adenomas releasing growth hormone (GH) and thyroid-stimulating hormone (TSH) are not considered to be plurihormonal." (PMID 28418929, 2017). "It remains unknown if PRL-secreting adenomas can produce antiangiogenic factors such as 16 kDa PRL." (PMID 25431591, 2014). "PRL and/or its inhibitor may directly influence adenoma vasculature." (PMID 25431591, 2014). "Phenotypically, adenomas were clinically non-functioning in 24 cases (48.97%), associated with acromegaly in 16 cases (32.6%), associated with Cushing's disease in 5 cases (10.2%), and with prolactin hypersecretion in the remaining cases (8.16%)." (PMID 19649482, 2009).
adenoma (continued). "Since PRL-secreting adenomas are the most prevalent form of pituitary tumors in human and they contain high levels of ERα mRNA and protein, these studies may have implications for the influence of phytoestrogens on the behavior of both normal and tumor tissues." (PMID 19400946, 2009). "Prolactin (PRL) hypersecretion is present in 30% of cases, either functional (secondary to impairment of hypothalamic production of dopamine or compression of the pituitary stalk by the tumor that impairs dopamine transport to the pituitary), or due to a mixed adenoma secreting both PRL and GH." (PMID 18578866, 2008). "Pathology confirmed a mature plurihormonal PIT-1 lineage adenoma immunopositive for TSH, GH, and prolactin with a Ki-67 of 3%." (PMID 42256640, 2026). "This case illustrates the rare presentation of a PIT-1 lineage adenoma secreting biologically active TSH, GH, and prolactin." (PMID 42256640, 2026). "In other case reports of ACTH-PRL secreting adenomas, immunohistochemistry has shown that adenoma cells can either be positive for both ACTH and PRL or consist of two distinct cell populations that are intermingled." (PMID 41201503, 2025). "Beyond tumor identification, distinguishing between adenoma subtypes, such as GH-, ACTH-, PRL-, and LH/FSH-secreting, would also be desirable." (PMID 40808829, 2025). "Hormonally active adenomas are mainly those that produce growth hormone (GH), adrenocorticotropic hormone (ACTH), prolactin (PRL), and rarely thyrotrophic hormone (TSH)." (PMID 40002261, 2025). "Seven cases (1.4%) with expression of 1 or 2 hormones of the PIT-1 lineage (HGH, PRL, TSH) were reclassified as plurihormonal PIT-1 positive adenomas." (PMID 40579705, 2025). "Multinominal regression analysis for the effects of baseline PRL, initial TSS, normalization of PRL at 12-month, and adenoma shrinkage equal of more than 50% at 12-month on the remission of prolactinoma." (PMID 41199869, 2025). "The patient underwent transsphenoidal surgery, and final pathology showed that the tumor was a plurihormonal adenoma of PIT1 lineage, immunopositive for GH and PRL, with a strong expression of somatostatin receptor subtype 2." (PMID 40725781, 2025). "For the entire cohort (N = 47), the mean age at diagnosis was 45.6 ± 17.6 years, with median prolactin levels of 70.0 ng/ml (IQR 51.0–103.4), and a mean adenoma diameter of 5.6 ± 2.0 mm." (PMID 40199840, 2025). "Both GH-secreting and PRL-secreting adenomas are classified as PIT1-lineage PitNETs, whereas ACTH-secreting adenomas belong to the TPIT lineage." (PMID 41470032, 2025). "The study cohort included 47 men with microprolactinoma [age at diagnosis 45.6 ± 17.6 years; median prolactin 70.0 ng/ml (IQR 51.0–103.4); low testosterone, 34 men (72.3%); adenoma diameter 5.6 ± 2.0 mm; median follow-up 7.1 years (IQR 3.5–10.4)]." (PMID 40199840, 2025). "Nineteen adenomas showed hormonal secretion: 11 secreted growth hormone (GH), 5 secreted adrenocorticotropic hormone (ACTH), 1 secreted both GH and prolactin (PRL), 1 secreted thyroid stimulating hormone (TSH) and 1 secreted follicle stimulating hormone (FSH)." (PMID 39681826, 2025). "We did not observe a statistically significant difference in the inhibition of PRL secretion by OCT, PAS and CAB between adenomas from patients with DA resistance and adenomas resected for other indications." (PMID 41184667, 2025). "Approximately 20% of CNFPAs are silent adenomas that immunostain for ACTH, GH, PRL, and TSH, or a variable combination of these hormones." (PMID 38612778, 2024). "There were 58 (69.0%) hypersecreting PAs (45 PRLomas, 7 GH secreting adenomas, 4 ACTH secreting adenomas, and 2 PRL-GH co-secreting adenomas) and 26 NFPAs." (PMID 39439563, 2024). "Gal-3 levels further increase in the progression from PRL and ACTH-secreting adenomas to carcinomas; gene methylation plays a role in Gal-3 expression, and RUNX1 and RUNX2 transcription factors seem to target its gene directly, enhancing its expression." (PMID 37958702, 2023).
adenoma (continued). "All 43 removed adenoma tissue samples used in our study stained immunohistochemically positive for somatotrophic hormone (STH), of which 14 were also positive for prolactin." (PMID 34674191, 2022). "The majority of PCs originate from functional PAs, most commonly from prolactin-secreting, followed by ACTH-secreting adenomas." (PMID 36157469, 2022). "Actually, in our series, we found hormonal co-secretion in the same hormones and the same order of frequency since six patients presented mixed adenomas: one with PRL/TSH and the others with PRL/GH." (PMID 36540468, 2022). "Seven patients turned out to have plurihormonal adenomas, consisting of 4 having GH/TSH, 2 GH/TSH/PRL, and 1 TSH/PRL." (PMID 36518240, 2022). "Among functioning adenomas, there were 2 PRL-positive adenomas, 1 GH-positive adenoma, 1 ACTH-positive adenoma, and 2 plurihormonal positive adenomas." (PMID 35634502, 2022). "The correlation between adenoma size and the severity of hormonal hypersecretion is well-established for prolactin-secreting tumors, and our findings support a linear correlation between ACTH and maximum adenoma diameter." (PMID 35329884, 2022). "The electron microscope and double immunofluorescence staining confirmed a plurimorphous plurihormonal adenoma producing TSH, GH, and PRL." (PMID 36539773, 2022). "As for the subtype that secretes prolactin (PRL), a case report described a huge PRL-secreting adenoma with the symptoms of dementia, which disappeared after a bromocriptine treatment." (PMID 36009154, 2022). "After six years, he referred to our Endocrinology Unit, revealing persistently increased PRL levels (2245 μg/L) despite CAB treatment (4.5 mg/week), with the persistence of a large residual adenoma." (PMID 34173929, 2021). "In accordance with the literature, combinations of GH/prolactin/TSH–FSH/LH adenoma (4/12), GH/prolactin/TSH–ACTH adenoma (3/12), and ACTH–FSH/LH adenoma (3/12) were observed." (PMID 34478014, 2021). "A study with a larger sample size supports the conclusion that PRL-secreting adenomas are more highly infiltrated by macrophages, while ACTH-secreting adenomas, gonadotrophin cell adenomas or NFPAs are infiltrated to a lesser extent." (PMID 34925244, 2021). "GR immunoreactivity was also demonstrated in many GH, prolactin (PRL), ACTH, TSH, follicle-stimulating hormone (FSH), luteinizing hormone (LH) α-subunit producing adenomas, null cell adenomas, and oncocytomas." (PMID 33808529, 2021). "PRL, GH and TSH stain were positive in 121 (70.8%), 107 (62.6%) and 40 (23.4%) PIT-1 positive adenomas, respectively." (PMID 34589436, 2021). "GH-producing adenomas had significantly lower EER and DER values than PRL-producing (P < 0.001) and NF adenomas (P < 0.001)." (PMID 33881731, 2021). "Among them, 18 reported on NFPAs, 13 on growth hormone (GH)-secreting adenomas, six on adrenocorticotropic hormone (ACTH)-secreting adenomas, four on prolactin hormone (PRL)-secreting adenomas, and 11 on craniopharyngiomas." (PMID 34638482, 2021). "In tumor tissues, pituitary GH- and PRL-secreting adenomas had diffuse VEGF distribution, while ACTH-, TSH-, and luteinizing hormone (LH)-secreting adenomas showed focal VEGF expression." (PMID 34869016, 2021). "Pituitary hormone co-staining was observed in 89 adenomas (65.4%), including 57 adenomas staining for both TSH and prolactin (PRL), 12 staining for ACTH, and 4 staining for FSH." (PMID 32843993, 2020). "The ACTH-adenoma cluster overexpressed miR4501, the CNFPA cluster overexpressed miR582, miR4774 and LINC01351, while the GH- TSH- and PRL-adenoma cluster overexpressed miR377 and miR136." (PMID 33168897, 2020). "The differentially methylated genes again showed the three groups, ACTH adenomas divided in two distinct gene-silencing patterns, one adjacent to non-functioning tumors cluster and the other adjacent to the GH-, TSH- and PRL cluster." (PMID 33168897, 2020).
adenoma (continued). "In GH-, PRL- and TSH-secreting adenomas genes such as SLIT1, PRLR and miR377 were upregulated due to demethylation." (PMID 33168897, 2020). "Pathway enrichment analysis revealed specific alterations of these clusters: calcium signaling pathway in CNFPA; renin-angiotensin system for ACTH-adenomas and fatty acid metabolism for the TSH-, PRL-, GH-cluster." (PMID 33168897, 2020). "Growth hormone (GH)—PRL-producing, GH-producing and follicle-stimulating hormone (FSH)—luteinizing hormone (LH)-producing adenomas were rare (11.1%, 5.6%, 5.6% of PAs, respectively)." (PMID 31044390, 2019). "D2R mRNA expression was demonstrated in two-thirds (12 of 18) of patients with an adenoma immunonegative for ACTH, GH, prolactin (PRL), and TSH." (PMID 30020466, 2019). "Prolactinomas and clinically NFPAs with positive GH and/or PRL immunostaining are also well described, while ACTH-secreting or TSH-secreting adenomas or gonadotrophin positive or null cell NFPAs are very rare." (PMID 29440248, 2018). "Out of 577 nonfunctioning adenomas, 180 were growth hormone (GH) secreting, 308 prolactin (PRL) secreting, 26 mixed GH/PRL adenomas, 68 adrenocorticotropin secreting, and 7 thyroid-stimulating hormone-secreting adenomas." (PMID 25270611, 2015). "He underwent trans-sphenoidal surgery and histology confirmed an adenoma with immunohistochemistry positive for ACTH, GH and prolactin." (PMID 24616766, 2013). "Radiological control is defined as the presence of a stable or decreasing adenoma diameter in all dimensions on conventional MRI, irrespective of prolactin levels." (PMID 41017446, 2026). "In the absence of increasing prolactin levels, one should consider alternative etiologies such as a nonfunctioning adenoma or postoperative changes." (PMID 41017446, 2026). "Idiopathic HPRL is characterized by mild to moderate elevated prolactin levels, normal pituitary MRI imaging without a visible adenoma, and excludes drug-induced HPRL, macroprolactinemia, chronic renal failure, and primary hypothyroidism." (PMID 40966237, 2025). "They explained that the impairment of cognitive function is related to the prolactin level but not to the size of the adenoma." (PMID 39361237, 2025). "A large size of the adenoma and baseline and failure in normalization of prolactin levels, were found to be relevant negative predictors of recovery from hypogonadism." (PMID 40035956, 2025). "In contrast, age, gender, initial treatment, adenoma shrinkage, and normalization of PRL did not predict long-term remission." (PMID 41178903, 2025). "We found that lower baseline and microadenoma independently predicted remission, while age, gender, initial treatment, adenoma shrinkage, and normalization of PRL did not predict long-term remission." (PMID 41178903, 2025). "One study reported a serum prolactin concentration >94 ng/mL to reliably distinguish between lactotrophs and non-functional adenomas." (PMID 39221401, 2024). "A notable exception was the synchronous co-expression of GH and PRL: their co-expression without an additional hormone indicates a mammosomatotroph adenoma and does not meet the criteria for a plurihormonal tumor." (PMID 38248047, 2024). "Tumor #2 was composed of 20% adenoma tissue (the remaining 80% comprised nontumor adenohypophyseal tissue); it stained positively for prolactin and negatively for reticulin and other adenohypophyseal hormones." (PMID 39876960, 2024). "A negative correlation was identified between adenoma size, volume, and prolactin level with testosterone levels." (PMID 38645431, 2024). "The BC rate of PRL-secreting adenomas varied obviously over time without a statistical difference (P = 0.273)." (PMID 37025271, 2023). "It was in all these cases a macroadenoma: a prolactin secreting tumor in six cases, two corticotroph adenoma, one somatotroph adenoma and non-functioning adenoma (NFA) in the remaining cases." (PMID 37391784, 2023).
adenoma (continued). "Co-secretory functioning adenomas were seen in 6.19% of cases, secreting both GH and PRL, but no immunohistochemistry confirmation was done." (PMID 37900080, 2023). "Just as in women symptoms such as amenorrhea are investigated at an early time-point, subsequent prolactin levels are usually not as high as in men harboring larger adenomas due to unreported or subclinical symptoms of hypogonadism." (PMID 35250868, 2022). "Non-functioning giant macroadenomas, including gonadotropin-secreting, silent corticotroph and null-cell adenomas, account for approximately 70% of all encountered subtypes, followed by prolactin-secreting (20%), GH and mixed GH-PRL (10%), while TSH secreting adenomas are exceptional." (PMID 36105410, 2022). "Attempts to link the progression of PRL-secreting adenomas to oral contraceptive use have recently proved negative and many studies have excluded this correlation." (PMID 35000899, 2022). "In this context, prolactin-secreting adenomas represent the majority of tumors, followed by non-functioning adenomas." (PMID 36675998, 2022). "Seven adenomas were non-functioning, six GH-secreting, one prolactin-secreting, and one ACTH-secreting." (PMID 35344185, 2022). "FPAs include growth hormone (GH)-, prolactin (PRL)-, adrenocorticotropic hormone (ACTH)-, thyroid-stimulating hormone (TSH)-, and follicle-stimulating hormone/luteinizing hormone (FSH/LH)-secreting adenomas." (PMID 36139495, 2022). "Histopathological confirmation was obtained in one patient (subject 18), while in the other predominant staining for prolactin and growth hormone (GH) was present without clear proof of adenoma or pituitary gland tissue (subject 13)." (PMID 35616762, 2022). "Previous cases also described plurimorphous plurihormonal adenomas producing TSH, GH, and PRL." (PMID 36539773, 2022). "This step will result in a dramatic rise in PRL levels if the patient has a MP, remaining unchanged in cases of non-functioning adenoma." (PMID 35000899, 2022). "Although rare, this artifact can lead to misclassification of a prolactin-secreting adenoma as a non-functioning lesion, thus having important implications for patient management." (PMID 34283370, 2022). "Metformin treatment reduced the cell viability in human ACTH-secreting adenomas and non-functioning adenomas, not so in GH-secreting and prolactin-secreting tumors, and did not affect hormone secretion, despite the high concentration used." (PMID 34884872, 2021). "The majority of the cystic pituitary adenomas were non-staining tumors (38.7% of adenomas), with prolactin- (31.2%) and ACTH-staining (11.8%) tumors following in prevalence." (PMID 34956896, 2021). "After the initial use of bromocriptine (with a consistent result on PRL secretion without adenoma shrinkage) CAB was initiated and increased up to 21 mg/week, achieving partial endocrine control." (PMID 34173929, 2021). "For endocrine-active adenomas, of 209 patients early biochemical remission was achieved in 148/209 (70.8%) patients: CD (55/81) 67.9%; GH (42/56) 75.0%, prolactinoma (46/66) 69.6%; TSH (3/3) 100%; GH-prolactin (1/2) 50%; GH-TSH (1/1) 100%." (PMID 34215990, 2021). "Moreover, BIM-23A760 molecule showed promising results in PRL- and TSH-secreting adenomas, when its antisecretory effect was compared with BIM-23A387, cabergoline or octreotide in primary cell lines." (PMID 33535394, 2021). "PD-L1 transcript and protein levels were found to be significantly increased in functioning (GH and prolactin-expressing) pituitary tumors compared to nonfunctioning (null cell and silent gonadotroph) adenomas." (PMID 33362722, 2020). "The GhrhrGpr101 mice developed chronic GH/PRL hypersecretion in the absence of adenoma or hyperplasia, indicating that Gpr101 overexpression can act as a powerful promoter of GH secretion in mice, even in a non-tumoral setting." (PMID 32958754, 2020).